IFNG (interferon gamma)
Diseases named in the same sentence as IFNG in open-access papers (continued):
Sharing a sentence is not in itself a finding about the gene and the disease.
tumor (continued). "Mechanistically, the tumor ecosystem drives its formation and development by (TGFβ)(pSTAT3) overcoming (IFNγ)(pSTAT1), exhibiting the 14 hallmarks of cancer." (PMID 38807760, 2024). "This was also associated with a decrease in CD8+ T lymphocytes that produced IFNγ, the potent anti-tumor cytokine." (PMID 39346903, 2024). "In I-E TME, these CTLs have a low expression of activation markers, granzyme B, and interferon gamma (IFN-γ), and are found at the tumor edges or “trapped” in so-called “fibrotic nests”." (PMID 38927974, 2024). "CD8+ T cells have a key role in tumor eradication through their capacity to specifically recognize tumor antigens and to secrete potent effector molecules for tumor cell killing such as IFNγ, TNFα and granzymes." (PMID 38956389, 2024). "Lactate acidosis is one of the factors that can regulate IFNγ expression in tumour-infiltrating NK cells and T cells, which negatively regulates IFNγ production by NK cells in the context of tumour transformation." (PMID 38339377, 2024). "The analysis revealed that the expression of T-cell effectors, including FasL, GZMB, PRF1, and IFNγ, was remarkably repressed in the tumor microenvironment." (PMID 39201460, 2024). "Without a doubt, IRF1 can be considered one of the most significant mediators of IFNγ action, both in tumor cells and in the cells of their microenvironment." (PMID 38396830, 2024). "Albeit IFNγ was decreased in tumor supernatants, intracellular staining in CD3+ cells revealed slightly increased IFNγ and TNFα signals after oxTAA injection." (PMID 38958560, 2024). "Studies have revealed that PD-L1 upregulation on tumor cells induces the expression of interferon-gamma (IFN-γ)." (PMID 38675717, 2024). "This tumour permissive environment is further enhanced by metastatic cancer cells hijacking the interferon gamma response, which is also enriched in ρ0D5 cells." (PMID 38751813, 2024). "In contrast, IL-10 treatment has surprisingly demonstrated antitumor efficacy, as shown with PEGylated IL-10, which induced the expression of IFNγ and granzymes in the tumor and induced the CD8+ T cell-mediated rejection of breast cancer models in mice." (PMID 39204319, 2024). "Ferroptosis in mDCs results in their inability to induce CD8+ T cells to produce IFNγ and leading to decreased antigen presentation anti-tumor abilities in the tumor microenvironment." (PMID 39192971, 2024). "This upregulation of PD-L1 expression in tumor cells and tumor-infiltrating immune cells happens largely as a response to the secretion of IFNγ and is part of the adaptive immune resistance." (PMID 38539530, 2024). "Stimulated IFNγ response is an immunomodulatory mechanism directed against infection, inflammation and anti-tumour activity." (PMID 39348343, 2024). "In line with tumor immunogenicity induced by itaconate, thimerosal also triggers tumor immunogenicity evidenced by significantly increased IL-2 promoter–driven LacZ activity and IFNγ production in T cells co-cultured with thimerosal-treated tumor cells." (PMID 39349845, 2024). "The reoviral treatment and aPD-1 demonstrated systemic memory through re-challenge rejection as well as increased systemic anti-tumor IFNγ-producing CD8+ T cells." (PMID 38803496, 2024). "IFNγ expression can also lead to tumor-repopulating cells entering dormancy through upregulation of IDO1/aryl hydrocarbon receptor (AhR) dependent-p27 induction but prevents apoptosis." (PMID 38216787, 2024). "The low amount of IFNγ produced by the CD56bright NK cells is surprising given how well they respond to tumor target lines in a co-culture functional assay." (PMID 39742279, 2024). "This approach substantially inhibited tumor growth and prolonged survival, potentially owing to increased intratumoral IFNγ post-anti-PD-1 treatment that likely renders Tregs more susceptible to KTC1101's inhibitory effects." (PMID 38486218, 2024).
tumor (continued). "Consistently, the CD45.1+ responder cell proportion among tumor lymphocyte infiltrates (TILs) was also increased, accompanied by an increased proportion of IFNγ + cells among CD8 TILs from Nrn1-/- Treg hosts." (PMID 39565188, 2024). "We found that the levels of inflammatory cytokines, such as IFNγ and TNFα, were increased in tumor-bearing mice." (PMID 38690266, 2024). "Intriguingly, cluster 6, which exhibited moderate differentiation state, was found highest expression level of transcription factors STAT1/STAT2-IRF9/IRF1 activated by interferon gamma (IFN-γ) leading to upregulation of tumor PD-L1 expression following RT." (PMID 38528587, 2024). "Interferon gamma (IFNγ) is another pleotropic cytokine that modulates T-cell differentiation and anti-tumor immunity and has also been used as a systemic immunotherapy, though now replaced by the more efficacious checkpoint inhibitors." (PMID 39602056, 2024). "Here, we identified a negative feedback loop in which reduced IFITM3 expression induces higher phosphorylation of STAT1, which promotes IFNγ responses in tumor-infiltrating Treg cells (TI-Tregs) and induces the fragility of TI-Tregs." (PMID 38167862, 2024). "Subsequently, dormant tumor cells were subjected to interferon-gamma (IFN-γ), an anti-tumor T-cell response product, to evaluate the responsiveness of distinct types of dormant cells (resting and inert) towards immune editing." (PMID 38795254, 2024). "M1 macrophages, induced by interferon-gamma (IFN-γ) and lipopolysaccharide (LPS), are pro-inflammatory and exhibit anti-tumor properties, marked by the production of IL-12, tumor necrosis factor-alpha (TNF-α), and inducible nitric oxide synthase (iNOS)." (PMID 39795180, 2024). "Vectorized IL-12 led to IFNγ production, infiltration of T cells and, ultimately, to tumor regression." (PMID 38558809, 2024). "b) A synergistic effect of CIK combined with CBD, resulted in a significant increase in tumor lysis and Interferon gamma (IFN-g) production." (PMID 38558822, 2024). "Here, stimulation with IFNγ increased median fluorescence intensity of PD-L1 expression about 4-fold in both tumor cell lines (p = 0.05 in both cases)." (PMID 39075115, 2024). "Upregulation of HLA class I expression by Interferon gamma (IFNγ) released by tumor-infiltrating T cell and alterations in IFNγ signaling pathways have been identified as mechanisms of resistance in other histologies." (PMID 39272933, 2024). "IFNγ was also shown to influence all stages of tumor “immunoediting” and control the balance between tumor promoters and suppressors in the tumor microenvironment, which is why it is considered a potential biomarker for cancer immunotherapy." (PMID 38396830, 2024). "IFNG and CXCR5 were significantly associated with tumor size (p = 0.032 and p = 0.047, respectively), and their expression was lower in invading tumors (T4)." (PMID 38831317, 2024). "Interferon‐gamma (IFNγ) is a well‐recognized T lymphocyte anti‐tumor cytokine, which significantly inhibits tumor growth and metastasis, and can better represent T lymphocyte activity." (PMID 38606362, 2024). "An in vivo study conducted using H22-bearing mice confirmed the upregulation of cytotoxic molecules expression, IFNγ secretion increasing, and reduction in tumor size after T-BET-IKDC administration." (PMID 38965548, 2024). "Since activated B cells can induce tumor cell death and IFNγ, B-cell vaccines are being examined for their therapeutic potential." (PMID 38672681, 2024). "These T cell pockets have higher local concentration of IFNγ (red/brown) than other areas of the tumor, and highest levels of IFNγ in the 25% PD-1+ T cell condition." (PMID 38636457, 2024). "They found that cps‐based monotherapy elicited a potent in vivo anti‐tumor immunological response driven by IFNγ‐expressing CD8+ T cells." (PMID 38109851, 2024).
tumor (continued). "The geometric arrangement of the ROR1 binding moieties impacts the release of IFNγ from T cells and their capacity to kill tumor cells in a ROR1 dependent fashion." (PMID 38455046, 2024). "It was found to be much more efficient at blocking tumor growth compared to murine IL-12, while stimulating significant IFNγ production with minimal toxicity." (PMID 39697343, 2024). "When the drug resistance-related Wnt/β-catenin signaling pathway is activated, IFNγ and NFκB signaling are inhibited in tumor cells, and down-regulate the expression of MHC-I molecules." (PMID 38962268, 2024). "We performed a dynamic in vitro killing assay with a 1:1 ratio of cognate, antigen-specific (PMEL), activated CD8+ T cells and B16-F10 tumor cells or IFNγ-pretreated B16-F10 tumor cells." (PMID 38636457, 2024). "Galectin-9 is secreted by cancer and myeloid cells upon induction by interferon β and γ (IFNβ and IFNγ) and has immunosuppressive roles in the tumor microenvironment." (PMID 38195762, 2024). "Addition of cabozantinib to anti-HER2 treatment enhanced IFNγ levels and reduced tumour growth via inhibition of Arg1+ MDSCs." (PMID 38464388, 2024). "Robust interferon signaling is a prominent feature of the TME in MIBC, and a high concentration of tumor interferon-gamma (IFN-γ) creates an immunosuppressive TME." (PMID 38216927, 2024). "In line with the progression, a lower IFNγ score (the average of the genes of the IFNγ signature, −1.937) was detected in the progressive lesion, while the PD-L1 expression on tumor cells was higher in the progressive lesion (10–50% vs. 1–10%)." (PMID 38280045, 2024). "The isolated splenic CD8+ cells elicited IFNγ production in response to neoantigens and showed superior cytotoxic effects on tumor cells." (PMID 38821980, 2024). "The immune desert is COX2+ but NOS2−; however, NOS2+ and COX2+ tumor satellites form in the inflamed areas near stroma-restricted CD8+ T cells that produce IFNγ." (PMID 39356141, 2024). "The Akt downregulates Treg cells while upregulates CD4+ and CD8+ tumor-infiltrating lymphocytes (TILs), leading to IFNγ expression and thereby inducing an anti-tumor immune response." (PMID 38715072, 2024). "Consistent with our prior results, we observed that mice vaccinated with Ad-AR-V7 with the addition of anti-PD1 had significantly more AR-specific responses in IFNγ ELISpot assays on splenocytes collected at humane endpoints or 66 days post-tumor-implantation." (PMID 39591176, 2024). "Tumor-intrinsic IFNγ signaling also regulates the expression of antigen presentation machinery and T-cell chemoattractants." (PMID 38635884, 2024). "Although PD-L2 is also inducible by IFNγ, like PD-L1, it displays a unique spatial distribution within the tumor microenvironment, implying discrete roles in immune evasion." (PMID 39687608, 2024). "Among them, angiogenesis, IL6-JAK-STAT3, IL2/STAT5, complement system, interferon gamma response, and G2M checkpoint, are crucial for tumour growth, inflammation, and immune system evasion." (PMID 39107713, 2024). "After the isolation of immune cells (peripheral blood lymphocytes), tumor‐reactive T cells are expanded in the presence of interferon γ (IFNγ)‐stimulated‐autologous PDO and then evaluated for their reactivity and ability to kill tumor organoids." (PMID 38962943, 2024). "Strikingly, the anti-IFNγ treatment of the cKO mice tumor model also showed similar tumor growth with WT mice, consistent with the IFNγ KO mice model." (PMID 38167862, 2024). "CAR-T cells effectively eliminate tumor cells through the release of perforin, granzymes, and cytokines, such as IL-1, IL-6, IL-15, interferon-gamma (IFN-γ), and GM-CSF." (PMID 38550613, 2024). "Infiltration of IFNγ-producing iNKT cells thereby positively correlated with better survival, demonstrating the importance of iNKT cells in the tumor setting." (PMID 39267746, 2024).
tumor (continued). "Apart from CD8+ T cells, CD4+ T cells also cooperate with IFNγ signaling through TNFα-p55 axis to induce tumor dormancy in a pancreatic cancer mouse model." (PMID 38216787, 2024). "As interferon-induced genes, STAT1 and IFITM3 were upregulated by IFNγ and other cytokines that induce Th1 response in the tumor microenvironment." (PMID 38167862, 2024). "Second, induction of the key T-cell-derived cytokine, IFNg, suggests that repolarization of TAMs translated to the activation of T cells within the tumor culture." (PMID 39199551, 2024). "This phenotype was driven by increased IFNγ-production in T cell populations, which infiltrated Dock2-deficient tumours, promoting IDO1 expression in tumour epithelial cells." (PMID 39242821, 2024). "Functional studies revealed that both tumor and non-tumor BTLA + CD4 + T-cells exhibited reduced capacity for IFNγ production compared to BTLA-CD4 + T-cells." (PMID 38233898, 2024). "Here, the authors show that HIF1α-controlled glycolysis is an important driver of IFNγ production in hypoxic T cells, governing anti-tumor immunity." (PMID 39477954, 2024). "SUV39H1 inhibition led to increased expression of granzyme B, perforin, FasL, and IFNγ, while a number of tumor-infiltrating CTLs remained unchanged in MC38 and CT26 colon tumor models." (PMID 39519018, 2024). "As expected, we found that direct coculture of LSS knockdown tumor cells with splenic stromal cells significantly impaired the level of IFNγ in splenic T lymphocytes." (PMID 38606362, 2024). "The TME of human ovarian tumors secretes CXCL9 in an IFNγ-dependent manner and thus recruits tumor-reactive T cells, conferring longer survival of patients and better response to checkpoint immunotherapy." (PMID 38786066, 2024). "Adaptive PD-L1 expression occurs in response to interferon-gamma, secreted by T-cells activated by tumor antigens and is mainly observed in the tumor-immune contact zone." (PMID 38953007, 2024). "Mice lacking all Ly49 receptors showed comparable results to mice lacking only inhibitory Ly49 proteins (Ly49I and Ly49C) in terms of reduced IFNγ production and tumor control." (PMID 39273034, 2024). "IL-33 blockade restricted SCC outgrowth, decreased Th2-derived IL-4 and increased the accumulation of Th1 IFNγ-producing cells in tumour-draining lymph nodes, and thus represents a promising SCC treatment strategy." (PMID 38662248, 2024). "IL12 has been shown to suppress VEGF effects in multiple tumor types through IFNγ and NK cell–mediated mechanisms." (PMID 38108458, 2024). "In striking contrast, attIL12-TILs promoted IFNγ production when interacting with autologous tumor cells to overcome immune suppression and maintain antitumor cytotoxicity." (PMID 39574893, 2024). "IFNγ not only directly facilitates tumor cell death by T cells but also indirectly promotes cytotoxicity via myeloid phagocytosis in the tumor microenvironment." (PMID 38893085, 2024). "In the tumor microenvironment, the interplay of TNF and IFNγ can be a prerequisite for controlling tumor development." (PMID 39723214, 2024). "Even IFNγ, which mediates critical steps of anti-tumoural immune responses, can, depending on signalling length and strength, promote tumour growth instead." (PMID 38831013, 2024). "Here the authors report that TP63 suppresses IFNγ signaling in SCC tumors and that its inhibition is associated with enhanced anti-tumor immunity and response to anti-PD1." (PMID 38509096, 2024). "Classification of tumors in our study relies on genes related to IFNγ signalling, which includes genes featured in the Tumor Inflammation Signature score – an algorithm designed for predicting patient response to pembrolizumab." (PMID 38755218, 2024).
tumor (continued). "The CXCR3-CXCL9/CXCL10 chemokine axis, mobilized by Th1 cells, can also participate in antitumor responses remodeling tumor immunity through the production of interferon gamma (IFN-γ)." (PMID 39769501, 2024). "We employed the TIDE database to examine tumor immune-related factors and observed significant correlations between Exclusion score, CAF, Merck18, MDSC, CD8, IFNG, and risk scores." (PMID 38900330, 2024). "Thirdly, IL-12 activates lymphocytes and NK cells to secrete IFNγ, which in turn exerts pleiotropic functions contributing to tumor growth inhibition." (PMID 37996514, 2024). "The second screening paralleled the first, yet it incorporated baseline IFNg stimulation to mimic native cytokine exposure within the tumor environment, if any." (PMID 38342608, 2024). "IL-12 is a potent antitumor cytokine that enhances T-cell and NK-cell activity, reverses tumor-induced immunosuppression, inhibits angiogenesis, and induces interferon gamma (IFNγ)." (PMID 39519758, 2024). "Tumor immunity Interferon-producing killer dendritic cells (IKDCs) produce IFNγ upon tumor recognition." (PMID 38965548, 2024). "Splenocytes (effector cells) were thawed and co-cultured with irradiated STOSE-luc (target cells) and an IFNγ ELISA technique was used to assess T-cell activation in response to exposure to tumor cells." (PMID 39276533, 2024). "When the mouse model was exposed to IBA, there was a reduction in the enhanced cytotoxic T‐cell infiltration induced by anti‐PD‐L1 antibody, a decrease in IFNγ and granzyme B expression, and significant resistance to tumor immunotherapy." (PMID 39503247, 2024). "The dysregulation of immune pathways, exemplified by the interferon-gamma (IFNγ) signaling pathway, emerges as another pivotal factor contributing to the facilitation of tumor immune escape." (PMID 38903504, 2024). "Interferon gamma (IFN-γ) secreted by activated CD 8+ cells down-regulates SLC7A11 leading to ferroptosis in tumor cells." (PMID 39670103, 2024). "The dysregulation of the IFNγ pathway is a complex event that can increase sensitivity to immune checkpoint blockade by attracting immune cells and inducing HLA expression on tumor cells." (PMID 38903504, 2024). "Immune activation by anti-tumor BsTE:T treatment in WT MC38-transplanted mice was evaluated by measuring serum interferon-gamma (IFN-γ) levels, which were stimulated by BsTE:T." (PMID 39105814, 2024). "Each spot within a well represents a splenocyte secreting IFNγ in response to target cells, suggesting the presence of systemic tumor-reactive T-cells." (PMID 39276533, 2024). "Our study suggests that treatment options that abrogate the TGFB2 mRNA expression, such as OT-101, combined with the delivery of interferon-gamma to the tumor microenvironment can improve the survival outcomes of pbDMG patients." (PMID 38255296, 2024). "Our study underlines a strong association between tumor cells with high MHC-II expression and the activation of the IFNγ-mediated pathway, which has been known for both MHC-II production and its hallmark as a T cell-inflamed signature." (PMID 39105803, 2024). "Intrinsic tumor factors, such as mutations in the JAK/STAT pathway, disrupt interferon-gamma signaling, impairing immune responses." (PMID 39518080, 2024). "As tumor of host sensing of IFNG was redundant and tumors were controlled without direct T cell cytotoxicity, multiple cell type targeted by IFNG should be controlled for tumor equilibrium." (PMID 38557819, 2024). "The detection of increased tumor CD8+ T cell infiltrates that are activated and able to produce IFNγ and GZMB and reduced tumor-associated Tregs when CpG-Stat3 siRNA is added to ICB therapy show that CpG-Stat3 siRNA can serve as an effective adjuvant for ICB." (PMID 39618825, 2024). "Subsequent studies indicated that IFNγ and arachidonic acid from the tumor microenvironment jointly induce tumor cell ferroptosis through ACSL4." (PMID 39402302, 2024).